TCHP (trichoplein keratin filament binding)
Description:
Tumor suppressor which has the ability to inhibit cell growth and be pro-apoptotic during cell stress. Inhibits cell growth in bladder and prostate cancer cells by a down-regulation of HSPB1 by inhibiting its phosphorylation. May act as a 'capping' or 'branching' protein for keratin filaments in the cell periphery. May regulate K8/K18 filament and desmosome organization mainly at the apical or peripheral regions of simple epithelial cells. Is a negative regulator of ciliogenesis.
Synonyms: MGC10854; TpMs
Tractability: Antibody: UniProt places it where antibodies can reach, with high confidence; its Gene Ontology location is reachable by antibodies, with high confidence. PROTAC: UniProt records ubiquitination sites on it; ubiquitination databases record sites on it.
Gene: Protein-coding gene on chromosome 12 (109,900,264 to 109,983,841, forward strand). Ensembl gene ENSG00000139437.
Subcellular location: Cytoplasm, cytoskeleton; Cytoplasm; Cell membrane; Mitochondrion; Cell junction, desmosome; Cytoplasm, cytoskeleton, microtubule organizing center, centrosome
Subcellular location (Human Protein Atlas): Cytosol; Plasma membrane; Basal body; Centrosome; Mid piece; Primary cilium; Principal piece
Gene Ontology:
Molecular function: protein binding
Biological process: apoptotic process; negative regulation of cell growth; negative regulation of cilium assembly
Cellular component: apical cortex; centrosome; cytoplasm; cytosol; keratin filament; mitochondrion; plasma membrane; cytoskeleton; desmosome; polymeric cytoskeletal fiber
Genetic constraint (gnomAD): Loss-of-function variants: 80 observed, 86.71 expected, observed/expected ratio (o/e) 0.92, 90% interval 0.77 to 1.11. The upper end of that interval is the gene's LOEUF score, 1.11, which puts it in group 4 of 6, group 1 being the genes least tolerant of losing a copy. Missense variants: 631 observed, 620.12 expected, observed/expected ratio (o/e) 1.02, 90% interval 0.95 to 1.09. Synonymous variants: 229 observed, 225.14 expected, observed/expected ratio (o/e) 1.02, 90% interval 0.91 to 1.13.
Homologues: Orthologues: chimpanzee TCHP (96% identical), macaque TCHP (94% identical), rabbit TCHP (57% identical).
Diseases named in the same sentence as TCHP in open-access papers:
TCHP is named in the same sentence as 154 diseases in open-access papers, as found by Europe PMC text mining. Sharing a sentence is not in itself a finding about the gene and the disease. The quoted sentences say what the papers report.
hepatocellular carcinoma (12 papers, 2015 to 2026). A malignant tumor that arises from hepatocytes. "In this study, we demonstrate that TCHP is markedly upregulated in hepatocellular carcinoma and hepatoblastoma and is associated with poor patient survival." (PMID 42034602, 2026).
liver cancer (5 papers, 2018 to 2026). An epithelial or non-epithelial malignant neoplasm that arises from the liver. "Trichoplein (TCHP), a centrosomal protein has recently been implicated in cell cycle progression, but its role in liver cancer remains unclear." (PMID 42034602, 2026). "Collectively, our findings establish TCHP as a potential oncogenic driver and therapeutic vulnerability in liver cancer and highlight the TCHP-AURKA axis as a promising target for synergistic treatment strategies." (PMID 42034602, 2026). "Importantly, TCHP inhibition not only suppresses tumor growth directly but also sensitizes liver cancer cells to the AURKA inhibitor alisertib, allowing tumor suppression at reduced drug doses and mitigating toxicity risks." (PMID 42034602, 2026).
Obesity (4 papers, 2014 to 2025). Accumulation of substantial excess body fat. "TCHP knockout mitigated high-fat-diet-induced obesity risks and inhibited adipogenesis in mice." (PMID 40004488, 2025).
ciliopathy (1 paper, 2020). A genetic disorder of the cellular cilia or the cilia anchoring structures, the basal bodies, or of ciliary function. "Because AURKA is also associated with both cancer and ciliopathy, these findings suggest that the involvement of KCTD17 and USP8 in cancer and ciliopathy might be mediated by effects on ciliogenesis via a TCHP–AURKA pathway." (PMID 32825105, 2020).
cancer (350 papers, 2006 to 2026). A tumor composed of atypical neoplastic, often pleomorphic cells that invade other tissues. "We previously demonstrated that trichoplein keratin filament binding protein (TpMs) exhibits hallmarks of a tumor suppressor gene in cancer-derived cells and human tumors." (PMID 32316593, 2020).
tumor (221 papers, 2007 to 2026). "Functional analyses revealed that TCHP overexpression accelerates hepatocarcinogenesis in mice, while its depletion suppresses tumor growth by inducing mitotic defects and extensive tumor cell death." (PMID 42034602, 2026).
TCHP also shares sentences with these, for which no sentence is quoted: breast carcinoma (72 papers); lung carcinoma (21); colon carcinoma (19); colorectal cancer (19); prostate carcinoma (17); gastric cancer (15); melanoma (14); cervical carcinoma (13); glioma (12); pancreatic cancer (12); ovarian carcinoma (11); glioblastoma (9); bladder cancer (8); leukemia (7); meningioma (7); non-small cell lung carcinoma (6); acute promyelocytic leukemia (5); brain tumor (5); schwannoma (5); viral infection (5); acute myeloid leukemia (4); clear cell renal cell carcinoma (4); infection (4); mesothelioma (4); neurofibromatosis type 2 (4); osteosarcoma (4); retinoblastoma (4); dementia (3); endometrial carcinoma (3); hepatoblastoma (3).
A further 118 diseases each share a sentence with TCHP in 3 papers or fewer.